KRTAP10-9 (keratin associated protein 10-9)
Description:
In the hair cortex, hair keratin intermediate filaments are embedded in an interfilamentous matrix, consisting of hair keratin-associated proteins (KRTAP), which are essential for the formation of a rigid and resistant hair shaft through their extensive disulfide bond cross-linking with abundant cysteine residues of hair keratins. The matrix proteins include the high-sulfur and high-glycine-tyrosine keratins.
Synonyms: KAP10.9; KRTAP18-9; KAP18.9
Tractability: No criterion of Open Targets' tractability assessment is met for any kind of drug.
Gene: Protein-coding gene on chromosome 21 (44,627,093 to 44,628,378, forward strand). Ensembl gene ENSG00000221837.
Pathways (Reactome):
Developmental Biology: Keratinization
Gene Ontology:
Molecular function: protein binding
Cellular component: cytosol; keratin filament
Genetic constraint (gnomAD): Loss-of-function variants: 1 observed, 1.62 expected, observed/expected ratio (o/e) 0.62, 90% interval 0.2 to 1.82. That is too few expected variants to judge how well the gene tolerates losing a copy. Missense variants: 391 observed, 381.74 expected, observed/expected ratio (o/e) 1.02, 90% interval 0.94 to 1.11. Synonymous variants: 199 observed, 159.23 expected, observed/expected ratio (o/e) 1.25, 90% interval 1.11 to 1.41.
Homologues: Orthologues: rat LOC120098854 (62% identical), rat Krtap10-9 (61% identical), rat Krtap10-1 (60% identical), mouse Krtap10-32 (57% identical), mouse Krtap10-30 (56% identical), mouse Krtap10-33 (56% identical), rat Krtap10-1l1 (56% identical), mouse Gm49918 (55% identical), mouse Krtap10-21 (55% identical), mouse Krtap10-23 (55% identical), mouse Krtap10-25 (55% identical), mouse Krtap10-26 (55% identical), and 24 more. Paralogues in human: KRTAP10-11 (86% identical), KRTAP10-6 (81% identical), KRTAP10-7 (81% identical), KRTAP10-4 (80% identical), KRTAP10-5 (78% identical), KRTAP10-2 (77% identical), KRTAP10-1 (73% identical), KRTAP10-10 (69% identical), KRTAP10-12 (68% identical), KRTAP10-3 (66% identical), KRTAP10-8 (62% identical), KRTAP16-1 (36% identical), and 35 more.